MXRA8 (matrix remodeling associated 8)
Diseases named in the same sentence as MXRA8 in open-access papers (continued):
Sharing a sentence is not in itself a finding about the gene and the disease.
tumor (continued). "In our study, patients with high MXRA8 expression had less CTL infiltration and higher TIDE and T cell exclusion scores so that MXRA8 may be involved in tumor immune escape through T cell exclusion." (PMID 36703779, 2022). "Nonetheless, the role of MXRA8 in tumor metastasis still requires further study." (PMID 36703779, 2022). "Overall, our data demonstrated that high MXRA8 expression in tumor cells could promote the therapeutic efficacy of OVM in several tumor types." (PMID 35393389, 2022). "Consistent with the result of HT29 cells, OVM reached a better therapeutic efficacy in HeLa and HepG2 tumors with MXRA8 expressing, and the total tumor weight was significantly reduced in MXRA8-expressing group treated with OVM compared to MXRA8-deficient group." (PMID 35393389, 2022). "In IHC staining, MXRA8 protein expression increased in tumor tissue." (PMID 36703779, 2022). "Thus, detection of MXRA8 expression in tumor is an essential step for designing individualized OVM therapy." (PMID 35393389, 2022). "Moreover, the AUC values presented that MXRA8 combined with tumor stage showed the best ability to predict OS among the factors analyzed." (PMID 36703779, 2022). "MXRA8 is one of the predicted tumor stroma-specific markers in various cancers." (PMID 33381521, 2020). "In addition, MXRA8 protein was present at high levels in metastatic tumor cells found in the lungs." (PMID 35456497, 2022). "MXRA8 appears to regulate these processes by altering genes like ADAMTS1 and TIE1 that influence the tumor microenvironment." (PMID 37762032, 2023). "MXRA8 promotes CRC invasion and metastasis through multiple mechanisms and is involved in tumor invasion and metastasis." (PMID 36703779, 2022). "In addition, our study revealed that MXRA8 expression correlated with the expression of multiple metastasis-associated chemokines (CXCL12, CXCL13, CCL9, CCL21, CXCR4, CXCR5, and CCR7), suggesting that MXRA8 may be involved in tumor invasion and metastasis by regulating the secretion of chemokines." (PMID 36703779, 2022). "Furthermore, MXRA8 was linked to the expression of several immune checkpoints in our work, including PD-1, PD-L1, PD-L2, CTLA-4, TIM-3, and LAG-3; thus, MXRA8 may be involved in tumor immune escape." (PMID 36703779, 2022). "In order to test which intracellular factors reflect the oncolysis ability of OVM cooperating with the receptor MXRA8, we compared the oncolytic ability of OVM with the ZAP, ERN1 or RHOQ expression in several tumor cells using Spearman’s correlation." (PMID 35393389, 2022). "The data showed that OVM had a better oncolysis on liver tumor tissues with MXRA8 positive staining compared to tumor with no MXRA8 expressing." (PMID 35393389, 2022). "Furthermore, we probed insight into the tumor selectivity of the OVM and offered a rationale for defining the expression of MXRA8 and zinc-finger antiviral protein (ZAP) in tumors as a potential dual-biomarker for OV precision medicine in future clinical use." (PMID 35393389, 2022). "To evaluate whether the promoting effect of MXRA8 for OVM could be a universal phenomenon, we tested several types of tumor cell lines." (PMID 35393389, 2022). "Four of 13 overlapped markers (MXRA8, CLMP, VCAN and FBLN1) are involved in cell adhesion and tumor metastasis, suggesting that dysfunctions in cell adhesion pathways could lead to anti-PD-1 resistance associated by RIPK1 and AXL." (PMID 36518525, 2022). "Moreover, through ectopic MXRA8 expression and ZAP knock-down, OVM resistant tumor cells were gradually transformed into sensitive cells." (PMID 35393389, 2022). "In the groups of MXRA8-expressing cells, the administration of OVM significantly inhibited tumor growth, while OVM-induced tumor suppression was nearly absent in HT29 cells without MXRA8 expression." (PMID 35393389, 2022).
tumor (continued). "Unlike the group of mice bearing MXRA8-expressing HT29 tumors treated with OVM, mice bearing vector-expressing HT29 tumors exhibited undetectable level of OVM in tumor tissues." (PMID 35393389, 2022).
cancer (10 papers, 2019 to 2025). A tumor composed of atypical neoplastic, often pleomorphic cells that invade other tissues. "Our results demonstrated that depletion of MXRA8 had profound effects on the proliferation, invasion, and migration capacities of PC-3 cells, suggesting its critical role in driving cancer progression." (PMID 38441550, 2024). "Overall, these evidences showed that MXRA8 is ubiquitously expressed in human solid tumor tissues and selectively upregulated in certain types of cancer, but MXRA8 expression also showed large individual differences among patients." (PMID 35393389, 2022). "To further clarify the role of MXRA8 in cancer, we conducted GSVA analysis of hallmark and KEGG pathways, showing that high expression of MXRA8 was positively associated with migration and immunosuppression." (PMID 36703779, 2022). "MXRA8 is a receptor for various articular viruses, but its role in cancer development and progression remains unsolved." (PMID 36703779, 2022). "MXRA8 has been scarcely any report in most cancers, but being of great importance for CRC prognostic." (PMID 36703779, 2022). "In consideration of the heterogeneity of MXRA8 and ZAP expression in cancers, we highlight the importance of using MXRA8 and ZAP as a potential dual-biomarker for predicting curative effects and selecting patients for OVM on multiple solid tumor types in clinical use." (PMID 35393389, 2022).
MXRA8 also shares sentences with these, for which no sentence is quoted: hepatocellular carcinoma (2 papers); kidney cancer (2); Arthralgia (1); Atrophy (1); cervical carcinoma (1); head and neck squamous cell carcinoma (1); Heat Stroke (1); liver fibrosis (1); lung adenocarcinoma (1); malaria (1); Obesity (1); pancreatic cancer (1); urothelial carcinoma (1); western equine encephalitis (1).